CEACAM5 (CEA cell adhesion molecule 5)
Diseases named in the same sentence as CEACAM5 in open-access papers (continued):
Sharing a sentence is not in itself a finding about the gene and the disease.
breast carcinoma (continued). "In summary, our work contributes to the investigation toward establishing whether CEACAM-targeting 2A3-CAR T-cells can potentially be used as an effective immunotherapeutic agent against CEACAM5/6-expressing human malignancies, such as pancreatic or mammary cancers." (PMID 38279989, 2024). "Furthermore, RT-PCR analysis on breast carcinomas confirmed the specificity of CB30 to CEACAM5." (PMID 33196697, 2020). "However, the exact role of CEACAM5 in breast cancer tumorigenesis remains unresolved." (PMID 33196697, 2020). "Moreover, reports on the proportion of CEACAM5-positive breast cancers vary greatly, from a few to more than 80%, which at least in part may explain the discrepancies with regard to the clinical value of this marker." (PMID 33196697, 2020). "Furthermore, the work of Powell and colleagues on a patient-derived xenograft (PDX) breast cancer model came to the conclusion that when establishing lung metastases tumor cells generally upregulated CEACAM5 in a process considered to be mesenchymal to epithelial transition (MET)." (PMID 33196697, 2020). "Therefore, we further investigated the functional role of CEACAM5 in breast cancer metastasis." (PMID 29736411, 2018). "Thus, the «group query» genes ERBB2, ESR1, CEACAM5 and AR are well known markers of breast cancer." (PMID 20158879, 2010). "To corroborate these immunohistochemical staining results, we performed western blotting on breast cancer cell extracts, and confirmed the specificity of CB30 and COL-1 for CEACAM5 as well as the cross-reactivity of 1105 with CEACAM6." (PMID 33196697, 2020). "CEACAM5 [Carcinoembryonic antigen (CEA)] is a protein, expressed in most lung and breast cancer as well as gastrointestinal cells." (PMID 29316915, 2018). "In locally advanced breast cancer, SLC7A5 and carcinoembryonic antigen-related adhesion molecules (CEACAM5 and CEACAM6) predict poor response of neoadjuvant chemotherapy." (PMID 29562706, 2018). "In immunoblot analyses Col-1 specifically detected human CEACAM5 at 180 kDa in human colon cancer cells HT29, and the canine antigen at 60, 120, or 180 kDa in CF33 and CF41 mammary carcinoma cells as well as in spontaneous mammary tumors." (PMID 21436956, 2011). "Interestingly, CEACAM5 and CEACAM6 facilitates metastatic progression of breast cancer, and CDH family is also known for their oncogenic role in several cancers including breast cancer." (PMID 40420099, 2025). "Generally, measuring CEACAM5-levels in serum is not considered for primary diagnosis in breast cancer, in large part because only a minor subset of patients has elevated levels." (PMID 33196697, 2020). "In this study, we initiated an investigation of CEACAM5, as there is still a lack of consensus on the consequence of CEACAM5-expression in breast carcinomas." (PMID 33196697, 2020). "Arguably, these data suggest a complex role of CEACAM5 in breast cancer and implies that both CEACAM5-positive and -negative cells can be directly involved in invasive and metastatic processes." (PMID 33196697, 2020). "In accordance with previous immunohistochemistry studies and being aware of the lack of a known canine CEACAM5 ortholog, our immunohistochemical analysis showed specific Col-1 staining in 23 of 30 canine mammary cancer patients." (PMID 21436956, 2011). "Pyllodes breast cancer is a stromal tumor, usually benign, and should therefore not express CEACAM5 or CEACAM6." (PMID 17201906, 2007). "NEO-201 is an IgG1 humanized mAb that binds specifically to tumor-associated variants of CEACAM-5 and CEACAM-6 expressed by colon, ovarian, pancreatic, non-small cell lung, head and neck, cervical, uterine and breast cancers, but is not reactive against most normal tissues." (PMID 35804808, 2022).
breast carcinoma (continued). "However, in one set, which is coincidently a male breast carcinoma, the lymph node lesion was negative for CEACAM5, while the primary tumor was heterogeneously positive." (PMID 33196697, 2020). "Moreover, the fact that 93% of CEACAM5-positive breast carcinomas in this study also express CEACAM6 suggests that multiple CEACAMs may act in concert, further complicating the consequences of CEACAM5-expression." (PMID 33196697, 2020). "Overall, the available data do not provide a consensus on the role of CEACAM5 in breast cancer." (PMID 33196697, 2020). "Thus, CEACAM5 facilitates tumor outgrowth at metastatic sites by promoting MET, warranting its investigation as a therapeutic target and biomarker of aggressiveness in breast cancer." (PMID 29736411, 2018). "Therefore, CEACAM5 and CEACAM6 may be promising targets for cancer immunotherapy including, perhaps, immunotherapy aimed at targeting breast cancer stem cells and metastatic disease." (PMID 23285151, 2012).
colon carcinoma (165 papers, 1976 to 2025). "CEACAM5 is an FDA-approved diagnostic tumor marker for colon cancer, with potential as a prognostic marker." (PMID 36741860, 2023). "The difference in pH-dependency can also explain why the carcinoembryonic antigen (CEACAM5) extracted from colon cancer tissue carries α-2,6-linked sialic acid instead of the α-2,3-linked sialic acid found in normal tissues." (PMID 31263697, 2019). "Our results imply that MUC2 downregulation is associated with increased expression of the tumor-associated antigens CEACAM5/6 in colon cancer." (PMID 28725043, 2017). "Altogether the hypermethylated CEACAM5 group showed these clinical features resemble the CMS1 classification of CRC with a BRAF mutation, TGFB2 mutation, MSI‐H, and proximally located colon tumor." (PMID 37942534, 2024). "Three colon cancer organoid models were selected based on their mRNA CEACAM5 expression level (RNA-sequencing)." (PMID 38087365, 2023). "Ceacam5, Klk6, Slc35d3, Postn, and Muc2 mRNA analysis improves the detection of tumor cells in the lymph nodes of colon cancer patients." (PMID 37996411, 2023). "CEACAM5, originally named Carcinoembryonic antigen (CEA), was first identified as a cancer-associated antigen in colon cancer." (PMID 33196697, 2020). "Prior studies have utilized a CEACAM5 antibody conjugated to a chemotherapy drug in colon cancer mouse models and demonstrated a reduction in tumor growth and increased survival." (PMID 32064046, 2020). "Further western blotting of mAb 6G5j conjugated to IR800CW demonstrated strong expression of CEACAM5 in 15 of 16 colon cancer lysates." (PMID 32064046, 2020). "Next, we screened all tagged CEACAM5 antibody-peptide constructs for their ability to penetrate cells and reach the cytosol using a LS174T colon carcinoma cell line, which expresses CEACAM5 at the cell surface." (PMID 31822703, 2019). "These properties have made CEACAM5 a prominent clinical cancer biomarker, widely used in early diagnosis, effective prognosis, and monitoring of colon cancer, as well as other types of cancers." (PMID 24858421, 2014). "The prototypic member of this family, human CEA (henceforth referred to as CEACAM5), was discovered by Gold and Freedman (1965) in the mid-1960s in the blood of patients with colon cancer." (PMID 24858421, 2014). "In dog 4, like in human HT29 colon cancer cells, Col-1 binding was observed at approximately 180 kDa corresponding to the molecular weight of human CEACAM5." (PMID 21436956, 2011). "Studies have shown that CEACAM5 affects expression of various groups of cancer-related genes, especially cell cycle and apoptotic genes, protecting colonic tumor cells from various apoptotic stimuli, such as treatment with 5-fluorouracil." (PMID 17201906, 2007). "Moreover, our data indicated that the hypermethylated CEACAM5 group showed molecular pathological features with a BRAF mutation, TGFB2 mutation, MSI‐H, and proximally located colon tumors that were similar to CMS1 tumors." (PMID 37942534, 2024). "Human colon cancer cell line LS174T, patient colon cancer lung metastases (lung 3, lung 4), regional and liver metastases (CM1, CM2, CM3, CM6, CM7, liver 2, liver 6, liver 5), peritoneal metastases (PM9, PM12) and primary colon cancer (C4 and C14) all demonstrated varying levels of CEACAM5." (PMID 32064046, 2020). "In addition, overexpression of at least two peptides corresponding to CD166, CD44, CD29, CEACAM5, biglycan, and cadherin 17 was detected in the colon tumour spheres." (PMID 20332776, 2010). "Importantly, overexpression of either CEACAM1 or CEACAM5 in CEACAM5-HLA-Ilow colonic tumor cells could prevent NK cytotoxicity against these cells." (PMID 21731662, 2011). "The Carcinoembryonic Antigen-Related Cell Adhesion Molecule 5 (CEACAM5) is a highly glycosylated protein, first recognized by Gold and Freeman in colon cancer in 1965." (PMID 40358697, 2025).
colon carcinoma (continued). "The human CEA (also named CEACAM5) and CEACAM6 have also been shown to be strongly positive in most colon cancers." (PMID 32064046, 2020). "CEACAM1, CEACAM5 and CEACAM6 have been demonstrated to be over-expressed in certain epithelial cancers, such as colon cancer." (PMID 32064046, 2020). "In particular, microfluidic perfusion stimulates expression of genes coding glycoproteins CEACAM5 and CEACAM6, prototype biomarkers for colon carcinoma." (PMID 30836980, 2019). "Similarly, a broad reduction in cell adhesion markers including CEACAM1, CEACAM5, CEACAM6, and CEACAM7 occurs in human colon cancer cell lines after treatment with chloroquine." (PMID 39900438, 2025). "Of all 21 colon cancer specimens, three (14%) did not express CEACAM5 and five (24%) showed a high expression of CEACAM5." (PMID 38087365, 2023). "mRNA analysis of CEACAM5, KLK6, and SLC35D3 improves the detection of tumor cells in lymph nodes from patients surgically treated for colon cancer, and, together with POSTN and MUC2, it further allows characterization of the tumor cells with respect to aggressiveness and the tumor cell environment." (PMID 34192710, 2021). "CEACAM1, CEACAM5 and CEACAM6 are co-expressed in epithelial cells of the gastro-intestinal tract and can also be over-expressed in endometrial, lung, ovarian, cervical, breast and colon cancers." (PMID 32064046, 2020). "Indeed, the tumorigenic functions of CEACAM5 had been demonstrated in both 3D culture of colon carcinoma cell lines in vitro and CEABAC transgenic mice in vivo; and a number of studies evidenced the contribution of CEACAM5 to tumor invasion and metastasis." (PMID 21731662, 2011). "We have recently reported that the humanized anti-CEA (CEACAM5) antibody, MN-14, can enhance the therapeutic effects of two cytotoxic drugs used frequently in colorectal cancer therapy, fluorouracil and CPT-11, in both subcutaneous and metastatic human colonic tumor cells propagated in nude mice." (PMID 17201906, 2007).
gastric cancer (151 papers, 1982 to 2026). A primary or metastatic malignant neoplasm involving the stomach. "In order to investigate the possible mechanisms associated with CEA and gastric cancer recurrence, cBioPortal was used to analyze genes correlated with CEACAM5 in mRNA expression level." (PMID 33391436, 2021). "To validate whether the mRNA level of CEA was associated with recurrence of gastric cancer, we downloaded mRNA expression data of CEACAM5 and clinical information from cBioPortal." (PMID 33391436, 2021). "The expression of CEACAM5 plays a critical role in both gastric adenoma and early gastric cancer, with a positivity rate of approximately 34–66% in early-stage gastric adenocarcinomas, suggesting its potential utility for early diagnosis." (PMID 40941034, 2025). "Fourteen out of sixteen gastric cancer specimens (87.5%) expressed CEACAM5 and were potential candidates for treatment with NILK-2301." (PMID 38087365, 2023). "CEACAM5, known as a marker indicating poor prognosis of gastric cancer, was weakly expressed in only 28.6% of incomplete intestinal metaplasia regions." (PMID 37196797, 2023). "Among the initial serum markers available for the diagnosis of gastric cancer are CEA (carcinoembryonic antigen/CEACAM5), CA72-4 and CA19-9, but they lack sensitivity and specificity." (PMID 37754493, 2023). "A specific and sensitive marker for colorectal and gastric carcinomas is the carcinoembryonic antigen-related cell adhesion molecule 5 (CEACAM5, CEA, CD66e) which is a membrane protein found on the surface of columnar epithelial and goblet cells of the colon." (PMID 31447859, 2019). "Four of these five integrations into STAD are in genes known to be up-regulated in gastric cancer, specifically CEACAM5, CEACAM6, TMSB, and CD74." (PMID 23840181, 2013). "Previous studies have noted the up-regulation of CEACAM5 in gastric cancers." (PMID 37196797, 2023). "In addition, the host genes (CEACAM5 and COL1A1) of these circRNAs were the important therapeutic and prognostic biomarker for gastric cancer." (PMID 35359600, 2022). "These CPP-KOAbs bind neither to LS174T nor to MKN45 (a gastric cancer cell line which also expresses CEACAM5), as determined by flow cytometry, demonstrating that the CPP alone does not mediate non-specific interaction with the cell surface." (PMID 31822703, 2019). "Interestingly, the TGF-β-R-initiated SMAD pathway was shown to target CEACAM5 (and CEACAM6) genes leading to CEA secretion as a mechanism for proliferation in gastric cancer cells." (PMID 25832000, 2015). "Although TROP2, CLDN7, and CEACAM5 were completely negative in adjacent normal regions, more than one-half of the regions of incomplete intestinal metaplasia, dysplasia, and gastric cancer expressed TROP2 (71.4%, 54.5%, and 53.8%, respectively) and/or CLDN7 (85.7%, 63.6%, and 63.6%, respectively)." (PMID 37196797, 2023).
pancreatic cancer (138 papers, 1994 to 2025). "Moreover, prostanoid and long-chain unsaturated fatty acid metabolic processes enriched in stemness-high pancreatic cancers were associated with CEACAM5 expression." (PMID 36494785, 2022). "CEACAM5 expression in pancreatic cancer also correlates with impairment of the tumoricidal function of M1 macrophages and neutrophils, although the mechanism is not fully understood." (PMID 41283511, 2025). "Overexpression of CEACAM5 is related to numerous cancers viz. breast, colorectal and pancreatic cancers." (PMID 40226632, 2025). "A humanized CEACAM5 mAb conjugated via a SPDB linker to DM4 (SAR408701) showed efficacy in vitro against pancreatic cancer cell lines." (PMID 37880707, 2023). "Lung tumor and pancreas tumor highly expressed CEACAM5 compared to normal lung and pancreas tissues." (PMID 36923424, 2023). "The levels of CEACAM5 were found the highest in the IFN-γ dominant pancreatic cancers which generate the most complex intra-tumour heterogeneity with a high proliferation rate." (PMID 36494785, 2022). "In this study, we found the impact of cancer stemness on immunotherapy responses to pancreatic cancer and identified CEACAM5 as a candidate stemness-related inhibitory immune checkpoint in pancreatic cancer." (PMID 36494785, 2022). "The inhibitory immune checkpoint CEACAM5 that was enriched in pancreatic cancers with high mRNAsi scores also exhibited a strong correlation with invasive cell-enriched signature and Msi+ tumour-initiating cell-enriched signature." (PMID 36494785, 2022). "Since the interplay between cancer stemness and the immune microenvironment affects cancer progression, we wondered which immune environment CEACAM5+ pancreatic cancers with high stemness tend to reside in." (PMID 36494785, 2022). "Our findings suggest that CEACAM5 is a candidate stemness-related innate immune checkpoint in pancreatic cancer, and is potentially regulated by prostanoid and long-chain unsaturated fatty acid metabolic processes." (PMID 36494785, 2022). "Levels of CEACAM5 expression were higher in the IFN-γ dominant pancreatic cancer than in the other immune subtypes of pancreatic cancer." (PMID 36494785, 2022). "Taken together, CEACAM5 was a potential stemness-related inhibitory immune checkpoint in pancreatic cancer." (PMID 36494785, 2022). "As prostaglandin E2 can shape an immunosuppressive barrier in the tumour microenvironment, the prostanoid metabolic process is likely to promote the immune resistance of CEACAM5+ stemness-high pancreatic cancers." (PMID 36494785, 2022). "Levels of CEACAM5 expression were higher in the interferon-γ dominant immune subtype of pancreatic cancers that are characterized by high M1 macrophage infiltration." (PMID 36494785, 2022). "Given that pancreatic cancer stemness negatively regulated anti-cancer immunity, we screened out CEACAM5, which was highly expressed in the high mRNAsi score group, among the 37 selected inhibitory immune checkpoint genes." (PMID 36494785, 2022). "Following the principle, our study revealed CEACAM5 as a candidate stemness-related inhibitory immune checkpoint in pancreatic cancer." (PMID 36494785, 2022). "Despite high infiltration of M1 macrophages and CD8+ T cells in the IFN-γ dominant pancreatic cancers, poor prognosis reflected the potential inhibitory effect of CEACAM5+ cancer cells on anti-cancer immunity in pancreatic cancer." (PMID 36494785, 2022). "MUC5AC and CEACAM5 have been shown to play a role in tumor progression and metastasis in pancreatic cancer." (PMID 33672926, 2021). "For three individuals ultimately diagnosed with metastatic breast, lung, or pancreatic cancer, CEACAM5 was a persistent longitudinal outlier as early as 26.5 months pre-diagnosis." (PMID 33004987, 2020). "In a feasibility study, anti-CEA CAR T cell therapy resulted in significant respiratory toxicities in patients with advanced CEACAM5+ gastrointestinal malignancies, including pancreatic cancer." (PMID 30319627, 2018).